MTCH2 (mitochondrial carrier 2)
Description:
Protein insertase that mediates insertion of transmembrane proteins into the mitochondrial outer membrane. Catalyzes insertion of proteins with alpha-helical transmembrane regions, such as signal-anchored, tail-anchored and multi-pass membrane proteins. Does not mediate insertion of beta-barrel transmembrane proteins. Also acts as a receptor for the truncated form of pro-apoptotic BH3-interacting domain death agonist (p15 BID) and has therefore a critical function in apoptosis (By similarity). Regulates the quiescence/cycling of hematopoietic stem cells (HSCs) (By similarity). Acts as a regulator of mitochondrial fusion, essential for the naive-to-primed interconversion of embryonic stem cells (ESCs) (By similarity). Acts as a regulator of lipid homeostasis and has a regulatory role in adipocyte differentiation and biology (By similarity).
Synonyms: MIMP; HSPC032; SLC25A50
Tractability: Antibody: UniProt predicts a signal peptide or a membrane-spanning region. PROTAC: ubiquitination databases record sites on it; its protein half-life has been measured.
Gene: Protein-coding gene on chromosome 11 (47,616,697 to 47,642,698, reverse strand). Ensembl gene ENSG00000109919.
Subcellular location: Mitochondrion outer membrane
Subcellular location (Human Protein Atlas): Mitochondria
Gene Ontology:
Molecular function: membrane insertase activity; protein binding
Biological process: protein insertion into mitochondrial outer membrane; protein localization to mitochondrion; lipid homeostasis; positive regulation of apoptotic process; positive regulation of stem cell differentiation; regulation of mitochondrial fusion; mitochondrion organization
Cellular component: membrane; mitochondrial outer membrane; mitochondrion; nucleus
Genetic constraint (gnomAD): Loss-of-function variants: 19 observed, 37.12 expected, observed/expected ratio (o/e) 0.51, 90% interval 0.36 to 0.75. The upper end of that interval is the gene's LOEUF score, 0.75, which puts it in group 3 of 6, group 1 being the genes least tolerant of losing a copy. Missense variants: 231 observed, 322.68 expected, observed/expected ratio (o/e) 0.72, 90% interval 0.64 to 0.8. Synonymous variants: 91 observed, 109.94 expected, observed/expected ratio (o/e) 0.83, 90% interval 0.7 to 0.99.
Homologues: Orthologues: chimpanzee MTCH2 (100% identical), macaque MTCH2 (99% identical), rabbit MTCH2 (96% identical), dog MTCH2 (94% identical), guinea pig MTCH2 (94% identical), mouse Mtch2 (94% identical), rat Mtch2 (85% identical), zebrafish mtch2 (69% identical), Drosophila melanogaster Mtch (35% identical), Drosophila melanogaster CG10920 (33% identical), Caenorhabditis elegans mtch-1 (28% identical), Caenorhabditis elegans F43E2.11 (13% identical). Paralogues in human: MTCH1 (47% identical).
Diseases named in the same sentence as MTCH2 in open-access papers:
MTCH2 is named in the same sentence as 51 diseases in open-access papers, as found by Europe PMC text mining. Sharing a sentence is not in itself a finding about the gene and the disease. The quoted sentences say what the papers report.
Obesity (39 papers, 2010 to 2025). Accumulation of substantial excess body fat. "Loss of MTCH2 results in mitochondrial fragmentation, an increase in whole-body energy utilization, and protection against diet-induced obesity." (PMID 39753955, 2025). "Genetic alterations in MTCH2 have been linked to various disease phenotypes, including obesity, Alzheimer’s disease and cancer." (PMID 41227324, 2025). "This study identifies mitochondrial carrier homolog 2 (MTCH2), an obesity susceptibility gene, as a negative regulator of energy homeostasis across flies, rodents, and humans." (PMID 40051328, 2025). "Genetic alterations in MTCH2 have been linked to diverse disease phenotypes, including obesity, Alzheimer’s disease, and cancer." (PMID 41044057, 2025). "The overexpression of MTCH2 is associated with lipid accumulation and obesity via its regulation of mitochondrial function." (PMID 40024983, 2025). "Adipose‐specific MTCH2 ablation enhances brown/beige adipose thermogenesis through Bcl‐2‐dependent autophagy, promoting energy expenditure and counteracting obesity‐associated metabolic disorders." (PMID 40051328, 2025). "pointed to the importance of MTCH2 as a highly expressed gene in the central nervous system in obesity susceptibility." (PMID 39588545, 2024). "Single-nucleotide polymorphism of mitochondrial carrier homolog 2 (MTCH2) is associated with obesity and increases fat accumulation in mouse muscle." (PMID 35406663, 2022). "Introgressed alleles dominate at the MTCH2 locus, associated with obesity/fat tissue in humans, and the DSP locus, essential for the proper development of epidermal skin in amphibians." (PMID 34178108, 2021). "MTCH2 is known to contribute to adipocyte function and regulation of lipid metabolism and to be genetically associated with obesity." (PMID 33947463, 2021). "Genome-wide association studies have linked MTCH2 with obesity, diabetes, and Alzheimer's disease (23, –, 25)." (PMID 33028634, 2020). "Loss of muscle MTCH2 protected mice from diet-induced obesity and hyperinsulinemia and increased energy expenditure." (PMID 29966015, 2018). "Recent publication shows that Mimp/Mtch2 loss in muscle leads to altered mitochondrial metabolism and protects from diet induced obesity and from hyperinsulinemia." (PMID 27359329, 2016). "Single-nucleotide polymorphism (SNP) in Mimp/Mtch2 (rs10838738) is associated with high body mass index (BMI) and common obesity in humans, increased weight, waist circumference and dietary intake and with decreased insulin sensitivity." (PMID 27359329, 2016). "The MTCH2-rs10838738 obesity risk variant was associated with a decreased ponderal index, however this association did not remain significant after accounting for multiple testing and it is therefore likely to be a chance finding." (PMID 21152014, 2010). "None of the 24 risk variants showed an association with birth weight and only the MTCH2-rs10838738 obesity risk-allele was nominally associated with reduced ponderal index (β = −0.13 kg/m3, 95%CI: [−0.23; −0.03], p = 0.01)." (PMID 21152014, 2010). "Notably, genome-wide association studies have identified MTCH2 variants associated with an increased risk of obesity and diabetes." (PMID 41227324, 2025). "Additionally, multiple genome-wide association studies have linked the MTCH2 locus to metabolic disorders such as diabetes and obesity." (PMID 39753955, 2025). "Notably, MTCH2 expression was downregulated following diet‐induced weight loss in patients with obesity, implying that Mtch2 levels are dependent on the prevailing adiposity and metabolic state." (PMID 40051328, 2025). "MTCH2 was among the genes with many novel likely pathogenic associations, which have been previously reported in genome-wide association studies focused on obesity and diabetes." (PMID 40355757, 2025).
Obesity (continued). "Subsequently, we selected one genome-wide significant SNP (rs4752856) for BMI, which is located on a circRNA derived from an obesity-associated gene (MTCH2; hsa_circ_0022025), and assessed the relative levels of the circRNA derived from the two alleles in vitro." (PMID 35879369, 2022). "Concordantly, there are associations observed between obesity and AD, suggesting that MTCH2 variants associated with AD and obesity may be acting, at least in part, through a common mechanism." (PMID 33947463, 2021). "Intriguingly, the entire locus, similar to variants in the MTCH2 locus, is implicated in obesity." (PMID 33947463, 2021). "MTCH2 variants have been associated with increased BMI, obesity, and diabetes." (PMID 32982666, 2020). "Collectively, these findings reveal MTCH2 as a conserved obesity‐linked factor in adipose tissue across species, and that elevated MTCH2 expression in adipose tissue may play a role in the negative regulation of energy homeostasis and metabolic dysfunction such as insulin resistance." (PMID 40051328, 2025). "Among them, MTCH2 emerged as a key regulator due to its established links to obesity and energy homeostasis." (PMID 40051328, 2025). "Collectively, these findings reveal a previously unrecognized regulatory mechanism whereby MTCH2 represses thermogenesis in obesity." (PMID 40051328, 2025). "In conclusion, our study identifies adipose MTCH2 as a key regulator of energy expenditure, with broad implications for understanding obesity and developing new treatments." (PMID 40051328, 2025). "To further explore the relationship between MTCH2 and obesity, we analyzed the correlations between MTCH2 expression and various clinical parameters." (PMID 41044057, 2025). "Our research identifies a novel role for MTCH2 as a crucial regulator of adipose tissue biology through its control of mitochondrial adaptation and thermogenesis during obesity." (PMID 40051328, 2025). "Our findings establish MTCH2 as a critical regulator of thermogenesis, offering new insights into its role in energy balance and its therapeutic potential in combating obesity and related metabolic disorders." (PMID 40051328, 2025). "Adipose‐specific knockout of MTCH2 protected against diet‐induced obesity and metabolic disorders, as evidenced by reduced fat deposition in adipose tissues and the liver, along with improved insulin sensitivity." (PMID 40051328, 2025). "Of the identified genes in our study, FTO, GNPDA2, MC4R, MTCH2, NEGR1, SH2B1, TMEM18 are unequivocally regarded as obesity genes associated with PCOS, as supported by contemporary evidence." (PMID 35679284, 2022). "Skeletal muscle-specific deletions of MTCH2 in mice results in increased mitochondrial mass and metabolism granting protection against diet-induced obesity." (PMID 33028634, 2020). "The genes reviewed here are FTO, NRXN3, NPC1, NEGR1, MTCH2, and GNPDA2, which were chosen for their association with obesity and their influence on NDgD or NDvD." (PMID 32982666, 2020). "Several obesity susceptibility loci in genes, including GNPDA2, SH2B1, TMEM18, MTCH2, CDKAL1, FAIM2, and MC4R, have been identified by genome-wide association studies." (PMID 32228543, 2020). "Our results also show that Mimp/Mtch2 is involved in lipid accumulation and uptake in cells and perhaps in human obesity." (PMID 27359329, 2016). "One group of genes (SERPINA12, CPE, SERPINA11, MTCH2, PNPLA5, INTS1, APOM) was associated (cosine value >0.1) with obesity and diabetes." (PMID 23544116, 2013). "Variants at MTCH2, LRRN6C and TMEM160 were also nominally associated with overweight or obesity risk." (PMID 23347264, 2013). "Other loci, including the INSIG2, TMEM18, KCTD15, SH2B1, MTCH2, GNPDA2, BDNF, or CHST8 genes, have also been associated with obesity." (PMID 24267414, 2013). "Thus, our studies suggest that the upregulation of adipose MTCH2 contributes to increased adiposity, disruption of thermogenesis, and metabolic disorder in obesity." (PMID 40051328, 2025).
Obesity (continued). "Interestingly, conditional knockout of MTCH2 in mouse skeletal muscle has been shown to protect against high-fat diet-induced obesity, likely due to increased whole-body energy utilization." (PMID 39753955, 2025). "Similarly, on Mexican mestizos, researchers found a link between obesity and various genetic variants like NEGR1, MTCH2, and SEC16B which are also prevalent in other ethnic populations." (PMID 40024983, 2025). "Notably, adipose‐specific MTCH2 depletion in mice protects against high‐fat‐diet (HFD)‐induced obesity and metabolic disorders." (PMID 40051328, 2025). "In HFD‐fed mice, Mtch2 mRNA expression was significantly upregulated in both scWAT and eWAT compared with chow‐fed mice, suggesting a positive relationship between Mtch2 expression and diet‐induced obesity." (PMID 40051328, 2025). "Based on these and other studies on CL and respiration mentioned in this review, it is tempting to speculate that BID regulates metabolism, obesity and respiration by interacting with and regulating MTCH2 activity." (PMID 41227324, 2025). "The link to metabolism originates from the identification of MTCH2 as a genetic susceptibility locus for obesity, with subsequent studies in conditional knockout mice demonstrating altered metabolic profiles in cells lacking MTCH2." (PMID 32094511, 2020). "However, the expression level of one obesity-related gene, MTCH2, in the majority of types of cancer tissues was higher than that in the corresponding normal tissues." (PMID 33299884, 2020). "This prompted us to examine the expression of Mimp/Mtch2 and its related genes in obesity." (PMID 27359329, 2016). "Among them, FTO, MC4R, MTCH2 and HTR2C are the main associated loci with BMI and obesity." (PMID 24267414, 2013). "In addition to these hypoxia-associated factors, several other novel transcripts demonstrated this divergent regulatory behavior, e.g. Dspg3 (dermatan sulphate proteoglycan 3) and the neuronally-responsive obesity-related gene Mtch2." (PMID 21738745, 2011). "Importantly from a therapeutic perspective, pharmacological or gene‐based interventions aimed at modulating MTCH2 activity could offer promising strategies for treating metabolic disorders such as obesity and insulin resistance." (PMID 40051328, 2025). "Interestingly, some genes associated with obesity were also associated with AD by different genetic approaches: candidate gene approach FTO, by differentially expressed genes NRXN3, NPC1, NEGR1, or by GWAS approach: LEPR, BDNF, TNFα, and MTCH2." (PMID 32982666, 2020). "Mtch2 is enriched in WAT and its expression is elevated in WAT in obesity, suggesting a role in promoting adiposity and regulating lipid homeostasis." (PMID 40051328, 2025). "Associations of the loci SH2B1 (rs7498665), near GNPDA2 (rs10938397), MTCH2 (rs10838738), and near MC4R (rs12970134) with obesity have been shown in many studies." (PMID 32228543, 2020). "Compared to the normal tissues, the five obesity-related genes (POMC, LEP, PCSK1, MTCH2, and GPR120) showed a similarity alteration of DNA methylation patterns in different cancer tissues." (PMID 33299884, 2020). "Compared to the normal tissues, five obesity-related genes (POMC, LEP, PCSK1, MTCH2, and GPR120) did show a similarity alteration of DNA methylation patterns in different cancer tissues." (PMID 33299884, 2020). "The MTCH2 expression was significantly higher in both scWAT and visceral WAT (visWAT) from individuals living with obesity (BMI ≥ 30) compared to lean individuals (BMI < 30), suggesting the relevance of MTCH2 to WAT in the context of obesity, which is consistent with previous studies." (PMID 41044057, 2025). "Collectively, these results demonstrate that the absence of adipocyte MTCH2 protects mice from HFD-induced obesity by enhancing energy expenditure." (PMID 41044057, 2025).
Obesity (continued). "Of the individual SNP analyses, only rs6548238 near TMEM18, rs10838738 in MTCH2, and rs7498665 near SH2B1 showed nominally significant interactions with physical activity level on BMI or obesity risk, but none survived adjustment for multiple comparisons." (PMID 20824172, 2010). "Although the mechanism of most genetic loci predispose individuals to obesity is not clear so far, evidence indicated that they were involved in energy uptake (FTO, MC4R, PCSK1, and BDNF) and adipocyte differentiation (FTO, TMEM18, BDNF, MTCH2 and NEGR1)." (PMID 24626232, 2014). "Although Mimp/Mtch2-GFP transgenic mice are not obese, evidence from cell lines and animal models supports the presence of obesity-related increases in renal and liver lipid accumulation." (PMID 27359329, 2016).
glioma (6 papers, 2021 to 2025). A benign or malignant brain and spinal cord tumor that arises from glial cells (astrocytes, oligodendrocytes, ependymal cells). "MTCH2 expression is closely associated with glioma progression, and its knockdown impairs cell migration and enhances temozolomide sensitivity of glioma cells." (PMID 33509092, 2021). "Bioinformatic analysis from TCGA and CGGA databases were used to investigate the association of MTCH2 with glioma malignancy and clinical significance." (PMID 33509092, 2021). "Bioinformatic data from public database and our cohort showed that MTCH2 expression was closely associated with glioma malignancy and poor patient survival." (PMID 33509092, 2021). "Silencing MTCH2 disrupted mitochondrial function, caused oxidative damage, impaired cell migration and invasion, inhibited the pro-survival Akt signaling pathway, and heightened sensitivity to temozolomide in glioma cells." (PMID 39948081, 2025). "MTCH2 is overexpressed in glioma, which is linked to a poor prognosis." (PMID 39948081, 2025). "Based on these results, we propose that MTCH2 knockdown may activate OXPHOs in glioma cells, and render cells more susceptible TMZ-induced apoptosis." (PMID 33509092, 2021). "MTCH2, present on the outer mitochondrial membrane, plays a crucial role in chemoresistance and tumor migration in gliomas." (PMID 36980325, 2023). "Abrogation of MTCH2 gene expression attenuated the invasive property of glioma cells and enhanced Temozolomide sensitivity via down-regulation of the AKT signaling pathway." (PMID 36980325, 2023). "In human glioma cells, MTCH2 knockdown increases the mitochondrial OXPHOs, which subsequently enhances oxidative damage in glioma cells." (PMID 36980325, 2023). "Western blot results showed that MTCH2 protein was extremely high in glioma cell lines, including U-87 MG, U-251 MG and A172 cells, in contrast to primary mouse neurons and astrocytes." (PMID 33509092, 2021). "Our work establishes the relationship between MTCH2 expression and glioma malignancy, and defines MTCH2 as a potential target for future interventions." (PMID 33509092, 2021). "Further examinations confirmed that the mRNA and protein levels of MTCH2 were increased in the tumor compared to matched adjacent tissues in our glioma cohort." (PMID 33509092, 2021). "The present study demonstrates that MTCH2, a critical protein in the mitochondrial outer membrane, regulates glioma malignancy including tumor migration and chemoresistance." (PMID 33509092, 2021). "Glioma cells with reduced MTCH2 expression have lowered invasion property and are sensitive to temozolomide." (PMID 33509092, 2021). "Results from TCGA showed that MTCH2 expression was positively correlated with glioma grade, and high MTCH2 expression tended to be associated with GBM subtype, coinciding with the fact that MTCH2 correlates with poor patient survival." (PMID 33509092, 2021). "siRNA-mediated MTCH2 knockdown were used to assess the biological functions of MTCH2 in glioma progression, including cell invasion and temozolomide-induced cell death." (PMID 33509092, 2021). "To explore the mechanistic interplay between mitochondrial dysfunction and glioma progression, we focused on mitochondrial carrier homolog 2 (MTCH2), a critical regulator of mitochondrial metabolism and related cell death." (PMID 33509092, 2021). "Silencing of MTCH2 expression impaired cell migration/invasion and enhanced temozolomide sensitivity of human glioma cells." (PMID 33509092, 2021). "To explore the biological function of MTCH2 in glioma cells, we first examined its expression pattern in glioma cell lines, compared with primary cultured brain cells, including neurons and astrocytes from embryonic mouse." (PMID 33509092, 2021).